TRBV12-5 (T cell receptor beta variable 12-5)
Description:
V region of the variable domain of T cell receptor (TR) beta chain that participates in the antigen recognition. Alpha-beta T cell receptors are antigen specific receptors which are essential to the immune response and are present on the cell surface of T lymphocytes. Recognize peptide-major histocompatibility (MH) (pMH) complexes that are displayed by antigen presenting cells (APC), a prerequisite for efficient T cell adaptive immunity against pathogens. Binding of alpha-beta TR to pMH complex initiates TR-CD3 clustering on the cell surface and intracellular activation of LCK that phosphorylates the ITAM motifs of CD3G, CD3D, CD3E and CD247 enabling the recruitment of ZAP70. In turn ZAP70 phosphorylates LAT, which recruits numerous signaling molecules to form the LAT signalosome. The LAT signalosome propagates signal branching to three major signaling pathways, the calcium, the mitogen-activated protein kinase (MAPK) kinase and the nuclear factor NF-kappa-B (NF-kB) pathways, leading to the mobilization of transcription factors that are critical for gene expression and essential for T cell growth and differentiation. The T cell repertoire is generated in the thymus, by V-(D)-J rearrangement. This repertoire is then shaped by intrathymic selection events to generate a peripheral T cell pool of self-MH restricted, non-autoaggressive T cells. Post-thymic interaction of alpha-beta TR with the pMH complexes shapes TR structural and functional avidity.
Synonyms: TRBV125; TCRBV12S5; TCRBV8S3
Gene: T-cell receptor variable (V) gene on chromosome 7 (142,580,917 to 142,581,427, forward strand). Ensembl gene ENSG00000275158.
Subcellular location: Cell membrane
Gene Ontology:
Biological process: cell surface receptor signaling pathway
Cellular component: plasma membrane
Homologues: Orthologues: macaque TRBV12-5 (92% identical), rat Trbv16 (67% identical), mouse Trbv16 (66% identical). Paralogues in human: TRBV12-3 (70% identical), TRBV12-4 (70% identical), TRBV11-3 (57% identical), TRBV11-1 (57% identical), TRBV11-2 (55% identical), TRBV7-6 (55% identical), TRBV7-7 (55% identical), TRBV7-9 (55% identical), TRBV17 (54% identical), TRBV7-3 (54% identical), TRBV7-4 (54% identical), TRBV7-2 (52% identical), and 39 more.